RNU6-411P (RNA, U6 small nuclear 411, pseudogene)
Gene: Small nuclear RNA gene on chromosome 6 (71,182,612 to 71,182,718, forward strand). Ensembl gene ENSG00000207180.
Homologues: Orthologues: chimpanzee U6 (100% identical), macaque U6 (91% identical), guinea pig U6 (84% identical), mouse Gm24919 (79% identical), rat LOC120096462 (71% identical). Paralogues in human: RNU6-1145P (91% identical), RNU6-38P (91% identical), RNU6-20P (90% identical), RNU6-468P (90% identical), RNU6-1 (89% identical), RNU6-1316P (89% identical), RNU6-15P (89% identical), RNU6-2 (89% identical), RNU6-25P (89% identical), RNU6-3P (89% identical), RNU6-41P (89% identical), RNU6-477P (89% identical), and 1289 more.